TCP1 (t-complex 1)
Description:
Component of the chaperonin-containing T-complex (TRiC), a molecular chaperone complex that assists the folding of actin, tubulin and other proteins upon ATP hydrolysis. The TRiC complex mediates the folding of WRAP53/TCAB1, thereby regulating telomere maintenance. As part of the TRiC complex may play a role in the assembly of BBSome, a complex involved in ciliogenesis regulating transports vesicles to the cilia.
Synonyms: TCP-1-alpha; CCT1; CCTA; D6S230E; CCT-alpha; IDDPMGS
Tractability: Small molecule: a structure with a bound ligand is known. PROTAC: ubiquitination databases record sites on it; its protein half-life has been measured.
Target class: Enzyme; Hydrolase
Gene: Protein-coding gene on chromosome 6 (159,778,498 to 159,789,703, reverse strand). Ensembl gene ENSG00000120438.
Subcellular location: Cytoplasm, cytosol; Cytoplasm, cytoskeleton, microtubule organizing center, centrosome
Pathways (Reactome):
Metabolism of proteins: Association of TriC/CCT with target proteins during biosynthesis; Cooperation of PDCL (PhLP1) and TRiC/CCT in G-protein beta folding; Folding of actin by CCT/TriC; Formation of tubulin folding intermediates by CCT/TriC; Prefoldin mediated transfer of substrate to CCT/TriC
Immune System: Gene and protein expression by JAK-STAT signaling after Interleukin-12 stimulation
Organelle biogenesis and maintenance: BBSome-mediated cargo-targeting to cilium
Gene Ontology:
Molecular function: protein binding; protein folding chaperone; RNA binding; ubiquitin protein ligase binding; ATP binding; ATP hydrolysis activity; ATP-dependent protein folding chaperone
Biological process: positive regulation of establishment of protein localization to telomere; positive regulation of protein localization to Cajal body; positive regulation of telomerase RNA localization to Cajal body; positive regulation of telomere maintenance via telomerase; protein folding; protein stabilization; scaRNA localization to Cajal body; tubulin complex assembly
Cellular component: centrosome; chaperonin-containing T-complex; extracellular exosome; microtubule; cytosol; acrosomal vesicle; cell body; Golgi apparatus; heterochromatin; microtubule organizing center; pericentriolar material; zona pellucida receptor complex
Genetic constraint (gnomAD): Loss-of-function variants: 6 observed, 53.88 expected, observed/expected ratio (o/e) 0.11, 90% interval 0.06 to 0.22. The upper end of that interval is the gene's LOEUF score, 0.22, which puts it in group 1 of 6, group 1 being the genes least tolerant of losing a copy. Missense variants: 508 observed, 705.71 expected, observed/expected ratio (o/e) 0.72, 90% interval 0.67 to 0.77. Synonymous variants: 225 observed, 241.83 expected, observed/expected ratio (o/e) 0.93, 90% interval 0.83 to 1.04.
Homologues: Orthologues: chimpanzee TCP1 (100% identical), macaque TCP1 (99% identical), dog TCP1 (98% identical), pig TCP1 (98% identical), rat Tcp1 (98% identical), guinea pig TCP1 (97% identical), rabbit TCP1 (97% identical), mouse Tcp1 (96% identical), tropical clawed frog tcp1 (88% identical), zebrafish tcp1 (87% identical), Drosophila melanogaster CCT1 (73% identical), Caenorhabditis elegans cct-1 (67% identical). Paralogues in human: CCT7 (34% identical), CCT5 (33% identical), CCT2 (33% identical), CCT3 (33% identical), CCT4 (30% identical), CCT8 (28% identical), CCT6A (26% identical), CCT6B (26% identical), PIKFYVE (24% identical), HSPD1 (19% identical), CCT8L2 (19% identical), MKKS (17% identical), and 1 more.
Diseases named in the same sentence as TCP1 in open-access papers:
TCP1 is named in the same sentence as 72 diseases in open-access papers, as found by Europe PMC text mining. Sharing a sentence is not in itself a finding about the gene and the disease. The quoted sentences say what the papers report.
breast carcinoma (18 papers, 2019 to 2024). "A recent study suggested that high mRNA expression of TCP1 was significantly associated with poor overall survival (OS) in patients with breast cancer." (PMID 34162426, 2021). "All of these, with the exception of TCP1, have also been linked to breast cancer, while FLNA, GSK3B and CCT2 are specifically linked to TNBC." (PMID 32127582, 2020). "In module #51, TCP1 functioned as a cytosolic chaperone in the biogenesis of tubulin, which has been proved to have an association with breast cancer." (PMID 30906311, 2019). "Here, the prognostic values of the “writer” enzymes and the TCP1 role in drug resistance in breast cancer (BC) were explored for further therapeutic strategies." (PMID 37818090, 2023). "Guestet al. identified that TCP1 together with CCT2 (TRiC subunit) are commonly altered in breast cancer and essential for the proliferation of breast cancer cells." (PMID 36239351, 2022). "TCP1 and the entire TRiC complex have been considered as potential therapeutic targets in breast cancer." (PMID 36239351, 2022). "Previous studies have shown that TCP1 plays an essential role in determining the overall survival (OS) of patients with breast cancer." (PMID 36239351, 2022). "Many tumors have TCP1 expression and TCP1 has been shown to be involved in drug resistance in breast cancer and ovarian cancer." (PMID 34750375, 2021). "TCP1 was essential for survival in breast cancer, and it was regulated by oncogene activation driven by PI3K signaling." (PMID 34162426, 2021). "To advance the discovery of new druggable targets for cell cycle inhibition, we investigated the role of Chaperonin-Containing TCP1 (CCT or TRiC) in breast cancer cells." (PMID 33996588, 2021). "However, a positive correlation between SAMHD1 and TCP1 expression was identified (p = 0.0081), confirming the transcriptomic data and pointing towards TCP1 as an additional factor determining SAMHD1 effect in breast cancer." (PMID 37667113, 2024). "Furthermore, in breast cancer cells, TCP-1 is an intracellular target of CT20p, as demonstrated in a study where alteration in the levels of the CCT ß-subunit resulted in altered susceptibility to CT20p." (PMID 36076292, 2022). "TCP1 could promote the growth of breast cancer cells and TCP1 overexpression, which significantly correlates with reduced overall survival of breast cancer patients." (PMID 34750375, 2021). "Comparative analysis with the well-established MCF-10A reference cell line revealed a significant upregulation of APOA5, CHAC1, EMID1, GOSR2, TCP1, and TMEM167A in breast cancer cell lines." (PMID 38300336, 2024). "TCP1 (P17987) expression is driven by oncogenic PI3K signaling in breast cancer, and we observe both elevated PGRMC1-dependent PI3K/AKT activity and TRiC abundance in DM cells." (PMID 32245408, 2020). "Aberrant TCP1 gene status has been detected in hepatocellular carcinoma, breast cancer and colorectal cancer, but no study has been performed for its effect in ESCC 29-31." (PMID 32047546, 2020). "Intriguingly, next three genes identified in our studies, which high expression correlates with poor prognosis of breast cancer patients, are the subunits of molecular chaperonin complex CCT/TRiC (CCT for chaperonin containing TCP1, also called TCP-1 ring complex)." (PMID 31101846, 2019).
ovarian carcinoma (9 papers, 2020 to 2024). A malignant neoplasm originating from the surface ovarian epithelium. "Morphologically normal cells upregulated 7 out of 8 proteins in the chaperonin containing TCP‐1 complex (adjusted P‐value = 7.64e‐15), which is critical for tubulin folding and has been previously associated with paclitaxel resistance in ovarian cancer." (PMID 32500953, 2020). "TCP1 encodes a molecular chaperone protein that modulates the PI3K/AKT/mTOR signaling pathway, thereby promoting ovarian cancer cell proliferation and enhancing drug resistance in acute myeloid leukemia." (PMID 38300336, 2024). "TCP1 is a factor that leads to breast and ovarian cancer resistance, and upregulation of TCP1 can promote CC progression." (PMID 37449209, 2023). "For instance, TCP1 has been found overexpressed in ovarian cancer, which is correlated with poor prognosis." (PMID 37818090, 2023). "TCP1 protein promoted the activation of PI3K/AKT1/mTORC1 signal in ovarian cancer, supposing that TCP1 played a tumor-promoting role in pancreatic cancer." (PMID 38304253, 2023). "Investigations have demonstrated that TCP1 is a factor being responsible for drug resistance in breast and ovarian cancer." (PMID 34750375, 2021). "High TCP1 expression was discovered in cisplatin-resistant ovarian cancer cell lines and the reducing TCP1 expression incremented cisplatin-induced apoptosis and the sensitivity of the cells to cisplatin as well, whereas, to date, the TCP1 role in leukemia remains unreported." (PMID 34750375, 2021). "Although the clinical importance of its subunits has been clarified in various carcinomas, the function of TCP1 in ovarian cancer (OC) remains unclear." (PMID 34162426, 2021). "Furthermore, analysis of data from the Kaplan–Meier plot showed a correlation between higher expression of TCP1, RPL5, HSPA4, and CCT5 and poor prognosis in ovarian cancer." (PMID 39309198, 2024).
hepatocellular carcinoma (8 papers, 2017 to 2023). A malignant tumor that arises from hepatocytes. "For example, there is a significant difference in the expression of TCP1/CCT2/CCT3/CCT4/CCT5/CCT6A/CCT7/CCT8 in hepatocellular carcinoma." (PMID 37058032, 2023). "In hepatocellular carcinoma, TCP1 regulates cell proliferation and migration by modulating the Wnt7b/β-catenin pathway." (PMID 37416927, 2023). "Hepatocellular carcinoma, for example, exhibits high levels of TCP1/CCT2-CCT8 expression and low levels of CCT6B, which leads to the abnormal regulation of Myc target genes and hypoxia-inducible factor target genes as well as cell cycle abnormalities." (PMID 36119498, 2022). "A similar correlation was observed with CCT1 (TCP1) and CCT2 in both hepatocellular carcinoma and colonic carcinoma, as well as with CCT2 in colorectal carcinoma." (PMID 29299146, 2017).
colorectal cancer (6 papers, 2012 to 2021). A primary or metastatic malignant neoplasm that affects the colon or rectum. "Clinically, TCP1 has been linked to colorectal cancer progression and to prevention of polyglutamate-containing proteins aggregation in neurodegenerative diseases like Huntington’s." (PMID 25647511, 2015). "Taken together, our data demonstrate TCP-1 is an efficient drug carrier for targeted therapy of colorectal cancer (CRC)." (PMID 27342639, 2016). "Our results indicated that targeted delivery of these two cytokines by TCP-1 peptide holds great promise for colorectal cancer therapy." (PMID 27342639, 2016). "Recently, we identified a vasculature-targeting peptide TCP-1 (CTPSPFSHC) using the in vivo phage library selection against an orthotopic colorectal cancer model." (PMID 23046982, 2012). "TCP-1 peptide was also found to be able to bind to some colorectal cancer cells (unpublished data)." (PMID 23046982, 2012). "TCP-1 peptide can specifically recognize the blood vessels of orthotopic colorectal cancer in normal BABL/c mice induced by syngeneic colon cancer cells (colon 26) and also orthotopic gastric cancer in nude mice induced by human gastric cancer cells (unpublished data)." (PMID 23046982, 2012). "TCP-1 peptide appears to be a promising agent in molecular imaging and drug delivery for human gastrointestinal cancers since preliminary data shows that it could also recognize the blood vessels in colorectal cancer samples in humans." (PMID 23046982, 2012). "If this situation can be reproduced in clinical setting, TCP-1 peptide conjugate combined with PET, MRI or endoscope may improve the diagnosis of patients with colorectal cancer." (PMID 23046982, 2012). "In fact the TCP-1 peptide isolated by our laboratory was found not to target the colorectal tumor induced subcutaneously by the same cell line or other colorectal cancer cells except to recognize the vasculature of orthotopic colorectal cancer (induced by mouse cancer cell in normal BALB/C mice)." (PMID 23046982, 2012).
acute myeloid leukemia (5 papers, 2021 to 2025). Acute myeloid leukemia (AML) is a group of neoplasms arising from precursor cells committed to the myeloid cell-line differentiation. "High TCP1 expression is also associated with chemotherapy resistance in ovarian cancer and acute myeloid leukaemia." (PMID 39174525, 2024). "Notably, TCP1 expression, which is increased in various tumours including breast, oesophageal, and liver cancer and acute myeloid leukaemia, is associated with poor prognosis." (PMID 39174525, 2024). "TCP1 presented high expression in acute myeloid leukemia cells, responsible for drug resistance." (PMID 37818090, 2023). "Moreover, the potential role of TCP1 in regulating drug resistance of various tumors including acute myeloid leukemia (AML) and lung adenocarcinoma (LUAD) has been investigated in recent studies." (PMID 37818090, 2023). "However, the TCP1 role in acute myeloid leukemia (AML) remains elusive." (PMID 34750375, 2021).
malaria (5 papers, 2013 to 2025). Malaria is a serious and sometimes fatal disease caused by a parasite that commonly infects a certain type of mosquito which feeds on humans. "One starting point would be the further development of the rapid-onset TCP-1 molecules (as such TPP for severe malaria is a product using a molecule from a sub-set of the TCP-1 portfolio)." (PMID 28086874, 2017). "No compound with pure TCP-4 activity currently exists within the global malaria portfolio: all the current compounds are dual-active TCP-1/TCP-4." (PMID 28086874, 2017). "Apart from fast TCP1 activity, it is also essential to stop the transmission of malaria from the patient to the next mosquito and to limit the fast evolution of resistance by the parasite to the drugs: “If you use only one drug, the parasite quickly develops resistance." (PMID 34959470, 2021). "Severe malaria products could also be included in this chart, as the sub-set of fast-acting TCP-1 molecules that are suitable for parenteral formulation." (PMID 28086874, 2017). "Following the identification of new molecules active against different Plasmodium stages, mainly with TCP1, TCP3, and TCP5 activity, the pipeline of medicines for the treatment of clinical malaria has been enlarged over the past years." (PMID 34959470, 2021). "There is no specific TCP for severe malaria, since such compounds are a discrete sub-set of TCP-1 provided they produce appropriate immediate and rapid parasite clearance, are well tolerated and can be developed as an injectable." (PMID 28086874, 2017).
Huntington disease (4 papers, 2010 to 2023). Huntington disease (HD) is a rare neurodegenerative disorder of the central nervous system characterized by unwanted choreatic movements, behavioral and psychiatric disturbances and dementia. "Downregulation of the TCP1 complex is linked to be common in neurodegenerative disorders such as Alzheimer’s, and Huntington disease." (PMID 37033372, 2023). "Incorrect protein folding leads to protein aggregation, and chaperonins containing the TCP-1 complex were reported to suppress aggregation in a Huntington’s disease model." (PMID 28453527, 2017). "TCP-1 disruptions are associated with the accelerated aging in SAMP8 animals, synaptic disruption in murine Huntington's disease models and is downregulated (as in CMP state) in aging rat synapses." (PMID 21179406, 2010).
Alzheimer disease (3 papers, 2016 to 2023). A progressive, neurodegenerative disease characterized by loss of function and death of nerve cells in several areas of the brain leading to loss of cognitive function such as memory and language. "This gene encodes a member of the chaperonin containing TCP1 (CCT) complex, which is impaired in severe neuropathies and in neurodegenerative disorders like Alzheimer's Disease (AD), where it is thought to promote toxic protein aggregates and cell death." (PMID 31998221, 2019).
colon cancer (3 papers, 2015 to 2021). "Yokota found TCP-1 was correlated with liver cancer and colon cancer, and the level of TCP-1 was positively related with the severity of the cancer." (PMID 26556873, 2015). "Expression of TCP1 was upregulated in 93% of HCC patients and 76% of colon cancer patients, while CCT2 was overexpressed in 100% of HCC patients and 82% of colon cancer patients." (PMID 34676169, 2021). "There are few reports of the relationship between TCP-1 and tumors; however, TCP-1 has been found to be correlated with the occurrence of liver cancer and colon cancer, and the content of TCP-1 was positively correlated with the severity of liver cancer and colon cancer." (PMID 26556873, 2015).
gastric cancer (3 papers, 2012 to 2022). A primary or metastatic malignant neoplasm involving the stomach. "TCP-1, a peptide targeting the vasculature of gastric cancer cells, was conjugated to tumor necrosis factor α (TNFα) to deliver the anticancer agent 5-fluorouracil (5-FU)." (PMID 35744930, 2022).
parasitemia (3 papers, 2017 to 2025). "An ideal TCP-1 compound, based on this review’s new definition, should be able to reduce parasitemia (PRRtot) 1012-fold by itself, based on curing adult patients with as high as 200,000 parasites/ml." (PMID 28086874, 2017). "This review has simplified the classification, describing all compounds with activity against blood stages as TCP-1, provided that they are predicted to be capable of a reduction in parasitemia of at least 106-fold in humans." (PMID 28086874, 2017). "However, our aim was to obtain candidate molecules with both target candidate profiles 1 and 5 (TCP-1, molecules that clear asexual blood stage parasitemia; TCP-5, molecules that block transmission by targeting the parasite), as desirable characteristics for candidate molecules." (PMID 32601162, 2020).
colorectal tumor (2 papers, 2012 to 2016). "In this study, we extended to study the effect of TCP-1/TNFα and TCP-1/IFNγ either alone or in combination in orthotopic colorectal tumor model in immune-competent mice." (PMID 27342639, 2016). "Here, we explored the antitumor effect of targeted TNFα or IFNγ in CRC through using fusion protein of TNFα or IFNγ with TCP-1 peptide, a novel ligand which can specifically bind to the vasculature of orthotopic colorectal tumors." (PMID 27342639, 2016). "We have previously established an orthotopic colorectal tumor model and identified a cyclic peptide known as TCP-1." (PMID 27342639, 2016). "Targeted delivery of TNFα by TCP-1 peptide displayed more potent antitumor activity than unconjugated TNFα by inducing more apoptosis and destructing neovasculature in orthotopic colorectal tumors at 24 h with the dose 5 μg/mouse." (PMID 27342639, 2016). "TCP-1/TNFα and TCP-1/IFNγ recombinant proteins were prepared and i.v. injected to study the in vivo anticancer effect in orthotopic colorectal tumor model." (PMID 27342639, 2016). "In the current study, the antitumor effect of TCP-1/TNFα and TCP-1/IFNγ alone or in combination was studied in orthotopic colorectal tumor model." (PMID 27342639, 2016). "TCP-1 peptide identified by our laboratory was labelled by FITC and administered to mice bearing orthotopic colorectal tumor for ex vivo detection under the blue light." (PMID 23046982, 2012). "Using phage display biopanning, we previously identified a novel cyclic peptide TCP-1 which can specifically bind to the vasculature of colorectal tumor in both animals and humans but not normal blood vessels." (PMID 27342639, 2016). "We have identified a tumor vasculature homing peptide (TCP-1 peptide) which targets only the vasculature of colorectal tumors but not normal blood vessels in animals and humans." (PMID 27342639, 2016).